HIF1A (hypoxia inducible factor 1 subunit alpha)
Diseases named in the same sentence as HIF1A in open-access papers (continued):
Sharing a sentence is not in itself a finding about the gene and the disease.
oral squamous cell carcinoma (57 papers, 2007 to 2026). "There is a similar study, which reported that oral epithelial dysplastic lesions with increased HIF-1α expression are at a high risk of malignant transformation to oral squamous cell carcinoma." (PMID 33154192, 2020). "Therefore, this study set out to investigate HIF-1α overexpression and its relationship with the aggressiveness and grade of oral squamous cell carcinoma (OSCC) and to explore the diagnostic potential of HIF-1α overexpression in OSCC in a cohort of Pakistani patients." (PMID 36766555, 2023). "The increase in HIF1A and VEGFA factors was shown to be significantly, directly, and positively associated with increased malignancy in other types of cancer, e.g., oral squamous cell carcinoma." (PMID 39888575, 2026). "In oral squamous cell carcinoma (OSCC), metabolic reprogramming drives fibroblast transformation into inflammatory cancer-associated fibroblasts (iCAFs) via Hypoxia-Inducible Factor 1 Alpha (HIF1A)-mediated CXCL12 expression." (PMID 41050070, 2025). "The elevated HIF-1a levels confirmed that our model for late-stage chemoresistant oral squamous cell carcinoma was suitable for further research." (PMID 41305000, 2025). "For instance, high expression of HIF-1α has been shown to be correlated with resistance to radiation on human oral squamous cell carcinoma cell lines." (PMID 38136171, 2023). "A study on the diagnostic value of 18F-FDG-PET in predicting tumor immune status found that tumoral PD-L1 expression in oral squamous cell carcinoma (OSCC) patients is suppressed by the activation of the HIF-1α–EMT axis." (PMID 35846323, 2022). "Reportedly, the interaction between the TLR4/NF-κB signaling pathway and HIF-1α contributes to tissue damage and tumor progression in pancreatic ductal adenocarcinoma, oral squamous cell carcinoma, and lung ischemia-reperfusion injury." (PMID 35464826, 2022). "HIF-1α was first reported to activate the transcription of HAS2-AS1 in oral squamous cell carcinoma under hypoxic conditions, and high levels of HAS2-AS1 were correlated with epithelial mesenchymal transition and tumor metastasis." (PMID 34094916, 2021). "Since HIF-1α is a primary regulator of the hypoxic response, an early study reported enrichment of miR-21 in exosomes derived from hypoxic oral squamous cell carcinoma cells was directly regulated by stable HIF-1α." (PMID 33088424, 2020). "Consistently, Qi demonstrated that in oral squamous cell carcinoma cells metformin significantly reduced the expression of HIF1A." (PMID 30217067, 2018). "In consist with our findings, a former study found that PD-L1 accompanied by HIF-1α surrounding necrosis in oral squamous cell carcinoma predicted a worse outcome." (PMID 28881642, 2017). "Recent studies have indicated an association between hypoxia inducible factor-1 alpha (HIF-1α) expression and poor prognosis in patients with oral squamous cell carcinoma (OSCC); however, definitive evidence of this association is yet to be obtained." (PMID 28521842, 2017). "The recent description of a crosstalk between TLR3 and HIF-1α in 2 oral squamous cell carcinoma cell lines raises the issue of the potential relationship between TLR3 and metabolic reprogramming in cancer cells." (PMID 27791989, 2016). "Specifically, we focused on pyruvate dehydrogenase (PDH), (hypoxia-inducible factor 1α) HIF-1α levels and the oral squamous cell carcinoma (OSCC) cell phenotype." (PMID 27474170, 2016). "Another study showed that HIF-1α can regulate angiogenesis and survival of oral squamous cell carcinoma." (PMID 25816356, 2015). "Beside the oral squamous cell carcinoma, this tight correlation between HIF-1α and VEGF were also found in laryngeal squamous cell carcinoma." (PMID 23762617, 2012). "For instance, Sal B may weaken glycolysis in oral squamous cell carcinoma through PI3K/AKT/HIF-1α signaling." (PMID 35502178, 2022).
oral squamous cell carcinoma (continued). "An earlier study demonstrated that nuclear overexpression of HIF-1α was detected in 69.64% of analyzed oral squamous cell carcinoma (OSCC), being positively correlated with the rate of tumor progression (tumor size, lymph node metastasis and histological differentiation)." (PMID 28592285, 2017). "In our previous study, we also found HIF-1α was overexpressed in oral squamous cell carcinoma." (PMID 25816356, 2015). "Also, we that HIF-1α was expressed in oral squamous cell carcinoma, and found that the levels of HIF-1α in human TSCC seemed to be correlated with human prognosis." (PMID 25816356, 2015). "Recent studies confirmed that hypoxia via HIF-1α might selectively up-regulate PD-L1 on immunosuppressive cells and solid tumors such as pulmonary pleomorphic carcinoma, and oral squamous cell carcinoma, which contributed to the evidence for hypoxia induced immune deficiency by PD-1 / PD-L1 axis." (PMID 28881642, 2017). "Methodology: Immunohistochemical evaluation of HIF-1α and HIF-2α was done in 90 samples of oral squamous cell carcinoma which were graded histologically into 30 samples each of well, moderately and poorly differentiated squamous cell carcinoma." (PMID 37842368, 2023). "Aim and objective: The aim of the study was to compare the expression of hypoxia-inducible factor 1α (HIF-1α) and hypoxia-inducible factor 2α (HIF-2α) in various histological grades of oral squamous cell carcinoma immunohistochemically." (PMID 37842368, 2023). "Previous studies have indicated that LPS-induced HIF-1α stabilization is mediated by the TLR4/NF-κB signaling pathway under normoxia in immune cells and oral squamous cell carcinoma." (PMID 35464826, 2022). "A feedback mechanism was found in oral squamous cell carcinoma (OSCC), where the activation of TL3 and TLR4 induced the expression of HIF-1α; in addition, HIF-1α bound to the promoter of TLR3 and TLR4, increasing their expression." (PMID 35565420, 2022). "A positive correlation has been observed between the levels of hypoxia-inducible factor 1-alpha (HIF-1α) and VEGF-C-stimulated lymphangiogenesis in oral squamous cell carcinoma." (PMID 30979062, 2019). "Specifically in patient derived primary oral squamous cell carcinoma cells, a negative correlation between radiosensitivity to γ‐rays and HIF‐1α is evident, and siRNA knockdown of HIF‐1α led to cellular radiosensitisation." (PMID 38899556, 2024). "Also, exosomes generated from hypoxic oral squamous cell carcinoma (OSCC) cells stimulate the migration and invasion of tumor cells in a HIF-1α and HIF-2α-dependent manner." (PMID 33639646, 2021). "The definition of BTV combining 18F-FDG-PET and contrast-CT is not the most robust way to define the hypoxic segment, even if is capable of defining more aggressive tumor types correlated with HIF-1a expression in patients with gastric, tongue, NSCLC, and oral squamous cell carcinoma." (PMID 30696472, 2019). "Metformin may render oral squamous cell carcinoma (OSCC) cells more sensitive to cisplatin; the expressions of GLUT1 and BCL-2, which are target genes of HIF-1α, are decreased as a result of the inhibition of the NF-κB/HIF-1α signaling pathway." (PMID 37460927, 2023). "Furthermore, patient-derived primary oral squamous cell carcinoma cells, grown under normoxic conditions, revealed an increase in nuclear translocation of HIF-1α following exposure to γ-rays and a negative correlation between radiosensitivity and HIF-1α protein levels." (PMID 36077667, 2022).
type 2 diabetes (56 papers, 2009 to 2026). "Another two studies claimed the insignificant association between HIF1A gene polymorphisms and type 2 diabetes." (PMID 35972942, 2022). "We confirmed the protective effect of a rare genetic variant of HIF-1α gene against type 2 diabetes in a Caucasian sample." (PMID 19691832, 2009). "In summary, a protective effect of the rare HIF-1α gene variant was proven against both, type 1 and type 2 diabetes, in a Caucasian sample." (PMID 19691832, 2009). "Therefore, the WWOX/HIF1A lowered expression ratio should be considered as a molecular risk factor for diabetes type 2 and gestational as we already reported." (PMID 35328751, 2022). "Furthermore, clinical studies have demonstrated that polymorphisms at the HIF1A locus influence the development of ischemic heart disease and have been associated with type 2 diabetes." (PMID 24502509, 2014). "Recently a non synonymous single nucleotide polymorphism (g.C45035T SNP, rs11549465) of HIF-1α gene, resulting in the p.P582S amino acid change has been shown to be associated with type 2 diabetes (T2DM) in a Japanese population." (PMID 19691832, 2009). "Separation of diabetic patients to type 1 (T1DM) and type 2 (T2DM) gave identical results demonstrating that the effects of HIF-1α gene variants are similar in type 1 and type 2 diabetes." (PMID 19691832, 2009). "Primary islets and beta cell lines readily become hypoxic under high-glucose conditions, and this is recapitulated in vivo in animal models of type 2 diabetes, and driven by HIF1α." (PMID 40133488, 2025). "Compared to the control group, serum levels of hypoxia-inducible factor (HIF)-1α were significantly elevated in patients with type 2 diabetes." (PMID 40727911, 2025). "Further, KEGG enrichment analysis demonstrated their significant enrichment in the HIF-1α signaling pathway (hsa04066), glycolysis/gluconeogenesis (hsa00010), and type II diabetes mellitus (hsa04930) pathways." (PMID 40989165, 2025). "The KEGG analysis of the 30 HGRMDEGs mainly revealed enrichment in the HIF-1α signaling pathway, glycolysis/gluconeogenesis, and type II diabetes mellitus pathway." (PMID 40989165, 2025). "Observational studies indicate that serum HIF-1α levels can predict vascular calcification in type 2 diabetes patients." (PMID 38962312, 2024). "Metformin is not only a famous type 2 diabetes treatment to improve metabolic dysregulation but also a HIF-1α inhibitor to decrease hypoxia-induced HIF-1α accumulation." (PMID 37460927, 2023). "Significantly, Set7_1a improved wound healing in a type 2 diabetic mouse model by activating HIF-1α signaling and downstream proangiogenic factors." (PMID 35859119, 2022). "In conclusion, this study demonstrates that type 2 diabetes alters the gene expression of HIF-1α and clock genes, which correlates with the degree of metabolic control." (PMID 32823749, 2020). "Research had suggested that the concentration of serum HIF-1α in type 2 diabetic patients was remarkably higher than that in the control group." (PMID 33456489, 2020). "Type 2 diabetes modifies the expression of HIF-1α and clock genes, which correlates with the degree of metabolic control." (PMID 32823749, 2020). "The impaired HIF-1α gene expression in patients with type 2 diabetes in comparison with controls merits further attention." (PMID 32823749, 2020). "In our study, the decrease in HIF-1α gene expression observed in type 2 diabetes was exacerbated in those patients with worse metabolic control." (PMID 32823749, 2020). "In contrast, an induction of HIF-1α by CoCl2 reduced proteinuria and histological markers of kidney injury in an obese type 2 diabetes model and in STZ-induced DN in rats." (PMID 28774305, 2017). "In contrast, an activation of HIF-1α by CoCl2 reduced proteinuria and histological markers of kidney injury in an obese type 2 diabetes model and in STZ-induced DN in rats." (PMID 28774305, 2017).
type 2 diabetes (continued). "In our previous study, the HIF-1α level in patients with type II diabetes mellitus and coronary calcifications was measured." (PMID 26223692, 2015). "In this study, we examined its effects on the development of type 2 diabetes by using adipocyte-specific HIF-1α knockout (ahKO) mice." (PMID 24705496, 2014). "The goal of this study was to determine the relationship between serum HIF-1α with coronary artery calcification (CAC) in patients with type 2 diabetes." (PMID 24564828, 2014). "In Japanese type 2 diabetes, HIF-1α is associated with type 2 diabetes and the P582S HIF-1α mutation was associated with type 2 diabetes by a consistently higher level of transcriptional activity than wild type, especially under hypoxic conditions." (PMID 24564828, 2014). "However, stabilizing HIF-1α before the onset of type 1 or type 2 diabetes normalized GFR, reduced oxygen consumption and proteinuria, ameliorated glomerular and endothelial damage, and counteracted renal metabolic alterations." (PMID 37626062, 2023). "The authors suggest that HIF-1α might be used as a therapeutic target for the β-cell dysfunction in type 2 diabetes mellitus (T2DM)." (PMID 37239097, 2023). "Notably, BCAT2, CD44 and HIF1A were directly related to the pathway of maturity onset diabetes of the young." (PMID 37904700, 2023). "Similarly, the expression of the proinflammatory cytokine IL1B mRNA and CXCL8 showed a clear trend of increase with a high correlation to HIF1A mRNA levels in samples from type 2 diabetic patients living at high altitude." (PMID 34651203, 2022). "miR-122-5p is involved in the inhibition of cardiac fibroblast differentiation induced by apigenin through targeting the transcription factor HIF-1α; it is regulated by another transcription factor HNF4α in type 2 diabetic mice, indicating a regulation between miRNA and TF in different diseases." (PMID 36203804, 2022). "PPAR-α agonist fenofibrate could improve endothelial function and increase the production of NO, and could consequently improve hypoxia and suppress the HIF-1α level in kidneys of type 2 diabetic mice." (PMID 34268320, 2021). "Diabetes type 2 increases fatty acid metabolism against the utilization of glucose through glycolysis; this leads to a reduction of succinate content which decreases HIF1-α levels in diabetic hearts." (PMID 32816039, 2020). "However, tissues from humans and animals with type 2 diabetes experience an altered cellular response to hypoxia that reduces the relative expression of HIF-1α, modifies glycolytic flux, and affects insulin secretion." (PMID 32823749, 2020). "•Type 2 diabetes blunts HIF-1α activation in ischemia and downstream adaptation to hypoxia." (PMID 30175272, 2018). "Our data extend previous findings that HIF-1α signaling is activated in the kidneys of experimental models with type I and type II diabetes and that it may be relevant to the development of DN." (PMID 28774305, 2017). "In conclusion, increased serum HIF-1α, VEGF, vWf, and IGF-1 and decreased serum 25(OH)VD3 may have an association with diabetic renal damage in type 2 diabetes patients." (PMID 27069929, 2016). "In type 2 diabetics, serum HIF-1α levels are closely related to coronary calcification." (PMID 24564828, 2014). "In type 2 diabetes patients with different urine albumin-to-creatinine ratios (UACR), serum HIF-1α concentrations were significantly elevated, along with significantly increased concentrations of serum BUN and serum creatinine." (PMID 39748872, 2024). "Intriguingly, reduced HIF-1α and HIF-1β/ARNT expression has been observed in the islets of type 2 diabetic patients." (PMID 38673770, 2024). "Among them, HIF1A may indirectly activate NLRP3, which encodes for NLRP3 inflammasomes, contributing to the inflammatory responses via IL-1β activation, which is down-regulated to a greater extent in BPD-DS in this study, and could be of key importance in the development of type 2 diabetes." (PMID 35739539, 2022).
type 2 diabetes (continued). "Results showed that, compared with the control group, serum levels of HIF-1α, VEGF, and vWf were significantly elevated in patients with type 2 diabetes and increased as urinary protein increased." (PMID 27069929, 2016). "At present, we found there to be a significant correlation between serum HIF-1α levels with UKPDS, HbA1c, and FBG in type 2 diabetes." (PMID 24564828, 2014). "Considering the significant role of HIF-1α in metabolic functions and the recent repositioning of PX478 for the treatment of type II diabetes, it is possible that consecutive dosing of PX478 over extended periods of time may lead to appetite suppression." (PMID 40244000, 2025). "Intriguingly, the treatment of diabetic mice with the HIF-1α inhibitor PX-478 improves insulin secretion and glucose tolerance, suggesting that the inhibition of HIF-1α might be a potential treatment for type 2 diabetes." (PMID 38673770, 2024). "In the case of type-2 diabetes mellitus (T2DM), abnormal metabolic phenotype of HIF-1α destabilization is noted as less tolerance to hypoxia and rapid HF progression and its stabilization by Molidustat was effective in the treatment of diabetic heart from post-ischemic recovery." (PMID 39472951, 2024). "Our study provides relevant information on levels of serum 25(OH)VD3, HIF-1α, VEGF, vWf, and IGF-1 in a large-scale cohort to further understand the law of their changes and to clarify their correlation in type 2 diabetes patients with different urine albumin creatinine ratio." (PMID 27069929, 2016). "Moreover, mRNA and protein levels of HIF1A were not differentially affected after exercise in skeletal muscle from individuals with type 2 diabetes as compared with NGT." (PMID 36070371, 2022). "To further increase our knowledge in this emerging field, we have designed a study to examine whether the expression of HIF-α subunits (HIF-1α and HIF-2α) is connected with changes in the expression of eight core circadian clock genes according to the presence of type 2 diabetes." (PMID 32823749, 2020). "Therefore, in patients with type 2 diabetes without cardiovascular symptoms, we aimed to: 1) examine the relationship between serum HIF-1α level and CAC; 2) evaluate the ability to predict the extent of coronary calcification." (PMID 24564828, 2014).